CREBBP (CREB binding lysine acetyltransferase )
Diseases named in the same sentence as CREBBP in open-access papers (continued):
Sharing a sentence is not in itself a finding about the gene and the disease.
tumor (continued). "Moreover, several epigenetic-related genes such as ARID1A, EP300, and CREBBP were also identified, highlighting the functional role of epigenetic modulation during tumor progression." (PMID 39334392, 2024). "Given their morphological and epigenetic similarities, circumscribed CNS tumors with EP300/CREBBP::BCOR(L1) fusions and CNS tumors with BCOR ITD may represent variants of the same tumor type." (PMID 38216991, 2024). "Notably, CREBBP was previously reported as a novel tumor suppressor, and CREBBP dysfunction was correlated with carcinogenesis and progression in several human malignancies." (PMID 36814797, 2023). "CREBBP/EP300 act as tumor suppressors and maintain normal hematopoietic function." (PMID 36831561, 2023). "CREBBP has thereby global effects on transcriptional regulation and the epigenetic landscape of cells, which might explain the involvement of CREBBP in tumor development." (PMID 37407554, 2023). "In addition, both tumor cohorts with poor and good responses to neoadjuvant treatment presented mutations in ARID1A, CREBBP, BRCA2 and RAD50, although with significantly different frequencies." (PMID 37373240, 2023). "Although more work is needed to understand the impact of these genes in RB pathogenesis, both BCOR and CREBBP are thought to be tumor suppressors; thus, their inactivation may contribute to disease severity." (PMID 37239954, 2023). "When we compared the mutation profiles from diagnosis with those from relapse or progression using paired tumor samples from four patients, truncated or nontruncated mutations were frequently found in CREBBP and BCL2 at the time of diagnosis and relapse." (PMID 36199784, 2022). "Furthermore, CREBBP and EP300 mutations are often mutually exclusive in DLBCLs, correlating with tumor recurrence and inferior clinical outcomes." (PMID 35773729, 2022). "Additionally, CREBBP and EP300 mutations contribute to the polarization of tumor-associated macrophages by increasing expression of CCL2, CSF1, and IL-10 via the Notch pathway." (PMID 35303910, 2022). "The importance of CREBBP and EP300 mutation is underscored following analysis of tumor tissues in several cohorts of patients with SCC of the head and neck, lung, or cervix treated with radiation therapy, identifying these mutations as associated with radioresistance and poor outcome." (PMID 34732714, 2021). "In this experiment, radiation or CREBBP KD (using two distinct shRNA constructs) alone had minimal-to-modest effect; however, the combination led to a profound tumor-growth delay, decreased tumor volume, and improved survival." (PMID 34732714, 2021). "In addition, the public data analysis in our current study showed enhanced CREBBP gene amplification in tumor specimens from BC patients who received hormonal therapy." (PMID 33827682, 2021). "Taken together, these results indicated that knockdown of CREBBP suppressed tumor growth in vivo." (PMID 34149923, 2021). "Both tumor volumes and tumor weights were dramatically reduced in CREBBP knockdown group." (PMID 34149923, 2021). "While the precise function of CREBBP in tumor biology remains largely unknown, several studies have reported that CREBBP and its closely related paralog EP300 behave as haploinsufficient tumor suppressors." (PMID 32493417, 2020).
tumor (continued). "Among ERGs that could be classified as tumor suppressors, KMT2D, KMT2C, ARID1A, ATRX, CREBBP, and PBRM1 were frequently mutated in many cancer types, whereas oncogenic ERGs were each mutated in specific cancer types, mainly IDH1 in LGG and DNMT3A in LAML." (PMID 32963031, 2020). "Mechanistically, these mutations tend to disrupt the original protein function, exemplified by the disrupted substrate binding in CREBBP and EP300, or to prevent the activation of a tumor suppressor, exemplified by mutations within the SMAD4 interface or CHEK2 activation loop (Dataset EV5)." (PMID 29572294, 2018). "VAFs of BCOR and CREBBP were well below 1, indicating that not all alleles were mutated and therefore possibly not all tumor cells harbored these secondary variants." (PMID 27126562, 2016). "Similarly, VAFs of BCOR and CREBBP and amplitudes of most of the large SCNAs were consistent with intra-tumor heterogeneity." (PMID 27126562, 2016). "Compared to negative expression, positive CREBBP expression was associated with a 2.417-fold increased risk for tumor recurrence (p = 0.003) and a 3.213-fold increased risk for progression (p = 0.011)." (PMID 25915404, 2015). "Similarly, investigations into the role of inactivating mutations in chromatin modifiers (i.e. KDM6A, CREBBP/EP300, SMARCB1) implicate many of these genes as tumor suppressors." (PMID 24622842, 2014). "Similarly, our findings also revealed that high CREBBP expression was associated with a favorable HNSCC prognosis, indicating that CREBBP might play a tumor-suppressive role in HNSCC." (PMID 36814797, 2023). "BRD of CREBBP/EP300 may be targeted to boost anti-tumor immune response." (PMID 36831561, 2023). "Overall, as the lack of recognition and presentation of tumor antigens by immune cells contributes to tumor invasion and progression, these findings suggest that CREBBP mutations directly promote lymphomagenesis by controlling the antigen presentation and interferon signaling pathways." (PMID 35022084, 2022). "Furthermore, expressions of NORAD and CREBBP were augmented while miR-877-3p was diminished in tumor tissues of the EV group, and EVs by silencing NORAD could antagonize the trend." (PMID 35281474, 2022). "Loss-of-function mutations in CREBBP also lead to the silencing of some genes involved in MHC-II-mediated antigen-presentation, suggesting that it may promote the immune escape of tumor cells." (PMID 35303910, 2022). "CREB‐binding protein (CREBBP) was mutated more frequently in tumours with high stromal CXCL8 and when further analysis was performed on the TCGA/PanCancer Atlas dataset (n = 594) there was a significant association between CREBBP mutation and higher CXCL8 mRNA expression (p < 0.001)." (PMID 35879507, 2022). "In B-lymphoma cells, the mutation or knockdown of CREBBP or EP300 inhibited H3K27 acetylation, downregulated FBXW7 expression, activated the NOTCH pathway, and downstream CCL2/CSF1 expression, resulting in tumor-associated macrophage polarization to M2 phenotype and tumor cell proliferation." (PMID 33431788, 2021). "In addition, mutations in CREBBP, EP300, TP73, RBL1, RBL2 and NOTCH family genes are largely mutually exclusive, suggesting that they may play similar tumor-promoting roles in the onset of SCLC." (PMID 34168983, 2021). "CREBBP and P300 genes may be involved in a variety of cellular activities, such as DNA repair, cell growth, differentiation, and apoptosis, as well as acting as transcriptional co-activators of tumor inhibition in different signaling pathways." (PMID 35173708, 2021).
tumor (continued). "Second, the novel ability to characterize tumor-specific somatic mutations in vivo, at diagnosis, creates opportunity for larger, prospective studies investigating the prognostic value of specific somatic RB1 alterations or other pathogenic mutations, such as BCOR or CREBBP." (PMID 33805776, 2021). "These preclinical experiments suggest that HDAC3-specific inhibition may be an effective therapy for GCB lymphomas, particularly those with CREBBP-mutations, by reducing the dominance of BCL6 on transcription programs and improving both terminal differentiation and immunogenicity of tumor cells." (PMID 35071240, 2021). "The CREBBP gene, mutated exclusively in the metastases of PTID 4, is an epigenetic modifier acting as a transcriptional coactivator through acetylation of histone proteins, thereby securing transcription of genes, including tumor suppressor genes and has thus been suggested as tumor suppressor." (PMID 29293529, 2018). "The CREBBP mutation in tumor T47 was not located in any of the CREBBP protein domains." (PMID 27126562, 2016). "Suspicion that CREBBP may be a tumor suppressor first arose in the mid-1990s, when heterozygous germline mutations were identified in the setting of Rubinstein-Taybi syndrome, a developmental disorder with an increased prevalence of cancer, including leukemia and lymphoma." (PMID 24622842, 2014). "CREBBP, CEBPA, and DNMT3A are tumor suppressor genes whose dysfunction has been reported in hematologic malignancies." (PMID 40216811, 2025). "We correlated epiRG scores with six major immune cell types and observed certain epiRG scores (CHD7‐mut, CREBBP‐mut, EP300‐mut) positively correlated with tumor proliferation." (PMID 40693457, 2025). "Inactivation of CREBBP and EP300 is considered a therapeutic strategy to achieve tumor radiosensitization due to impaired homologous recombination repair." (PMID 41301688, 2025). "Epigenetic regulators like CREBBP and SETD2 control gene expression through histone modifications, with their dysregulation leading to tumor development." (PMID 39273340, 2024). "These combined approaches enabled the identification of six tumour suppressor driver genes—namely BAP1, CREBBP, FAT1, NCOA6, RAD21 and UBR5—as regulators of the DDR and maintenance of chromosomal stability in NSCLC." (PMID 39738653, 2024). "CREBBP is a widely expressed transcriptional coactivator and a major lysine acetyltransferase (KAT), involved in histone acetylation and contributing to tumour recurrence, invasion and migration." (PMID 38493218, 2024). "Inhibition of CBP/CREBBP and EP300 activity in vitro and in vivo blocks tumor growth in neuroblastoma, pancreatic cancer, and acute myeloid leukemia." (PMID 37509254, 2023). "CN470 has notable anti-tumor activity against MLL1-rearranged ALL by binding to the bromodomains (BRDs) of BRD4, CREBBP, and EP300 in vitro and in vivo." (PMID 36831561, 2023). "Based on these observations, we set out to examine the impact of combined CREBBP and KMT2D haploinsufficiency in vivo and explored how these two tumor suppressors functionally interact in normal and malignant GC B cells to promote oncogenesis." (PMID 36893259, 2023). "This study is the first to examine the SCNA status of both AH and tumor samples while simultaneously analyzing RB1, BCOR, CREBBP, and MYCN for SNV disease drivers." (PMID 37239954, 2023). "Inhibition of CREBBP/EP300 with GNE-781 impairs the differentiation of human CD4+ T-cells into Tregs, providing a therapeutic approach by promoting a pro-inflammatory tumor microenvironment." (PMID 36831561, 2023). "Here we use CPI-1612 to demonstrate that inhibition of CREBBP/EP300 HAT activity represents a promising strategy to suppress ER-mediated proliferation and tumor growth." (PMID 35353838, 2022).
tumor (continued). "In this review, first we describe the most frequent epigenomic alterations in FL (KMT2D, CREBBP and EZH2) that affect the immunological niche, and their potential consequences on the informational transfer between tumor B cells and their microenvironment." (PMID 35022084, 2022). "Epigenetic alterations relating to histone methylation (KMT2D, KMT2C, EZH2), histone acetylation (CREBBP, EP300), and DNA methylation (TET2) play an important role in tumor progression for FL and DLBCL." (PMID 36497332, 2022). "Functional analysis confirms an oncogenic role for the ZMIZ genes, and tumor suppressive roles for KMT2C, CREBBP and NCOA2, in the initiation or progression of human cuSCC." (PMID 34398873, 2021). "In PDX models, HDAC3 inhibition with BRD3308 reduced tumor growth, and induced upregulation of BCL6 target genes and MHC-II expression in the setting of both CREBBP-mutant and CREBBP-WT diseases." (PMID 35071240, 2021). "Not only are 16p13 abnormalities a novel association in dFL, we also found that the minimally altered region(s) encompassed CREBBP, CIITA, and SOCS1, which suggests a possible co-operative mechanism for tumor immune evasion." (PMID 32555149, 2020). "Therefore, CREBBP may be considered as a tumor therapeutic target in DLBCL patients." (PMID 31366566, 2019). "In SCLC, mutations clustered in the HAT domain, as well as gene truncation in the CREBBP and EP300 acetyltransferases suggest a potential role of H3K27 acetylation and the resulting gene activation in tumor suppression." (PMID 31827074, 2019). "Pifithrin-μ, also known as 2-phenylethyenesulfonamide (PES), is a heat shock protein 70 (HSP70) inhibitor that disrupted the interaction between CREB1 and CREB-binding protein (CREBBP), ultimately suppressed SESN3 to enhance the anti-tumor effects of sorafenib." (PMID 39863613, 2025). "Although transcriptomic levels varied significantly between tumor and normal tissues, methylation levels of most ACRGs did not, except for CREBBP, which was consistently hypomethylated across 15 tumor types." (PMID 39906742, 2024). "Our data identify a direct biochemical and functional interaction between CREBBP and KMT2D in the GC, with implications for their role as tumor suppressors in FL/DLBCL and for the development of precision medicine approaches targeting enhancer defects induced by their combined loss." (PMID 36893259, 2023). "Likewise, KMT2C, CREBBP, and NCOA2 were identified to demonstrate tumor-suppressive roles in the initiation and progression of human cSCC." (PMID 36980718, 2023). "The tumor cells did not express CREBBP, but strongly expressed MYCN as expected based on their genotype." (PMID 37407554, 2023). "For example, gene CREBBP is a known tumor gene, and it does not show a connection with PIK3CA in the normal state, but it can be regulated by PIK3CA in tumor state." (PMID 34335688, 2021). "CREBBP depletion in A431 cells did not result in a change in tumor volume and this gene was not assayed in vivo using the other two cuSCC cell lines." (PMID 34398873, 2021). "Next, we investigated whether down-regulation of CREBBP, KMT2C or NCOA2 could promote tumor progression in cuSCCs." (PMID 34398873, 2021). "In the context of cancerogenesis, CREBBP and EP300 act as tumor suppressors." (PMID 28302137, 2017). "Among the proteins that showed distinctive expression in the AbM profiling, 2 representative proteins, CREB-binding protein (CREBBP) and CD81, were chosen, and their prognostic significance for tumor recurrence and progression were investigated in an independent primary HG NMIBC cohort." (PMID 25915404, 2015).
tumor (continued). "Similarly, univariate Cox regression analyses showed that CREBBP and CD81 expression were significant predictors for tumor recurrence and progression." (PMID 25915404, 2015). "With IVA, there was four bone-related processes brought front only in the case of the tumour tissue—“myelopoiesis of bone marrow” (NPM1, RARA), “quantity of trabecular bone” (CREBBP, SMO), “outgrowth of bone marrow cells” (ALK) and “inflammatory response of bone marrow-derived macrophages” (RELA)." (PMID 25496518, 2014). "However, the tumor/normal log2 ratios of AXIN1, CREBBP, GSK3A, and NKD2 in the BRAF wildtype samples were low (−0.26 median, 0.12 standard deviation) compared with those in the BRAF mutated samples (−0.02 median, 0.12 standard deviation)." (PMID 23324568, 2013). "The cMS repeats in CREBBP and EP300 are short and unlikely to be mutated in a high proportion of MSI-High tumours." (PMID 21209843, 2010). "CREBBP and SUV39H1 upregulation was observed in breast cell lines compared tobreast tumours." (PMID 16638127, 2006). "However, only EP300 and not CREBBP was significantly upregulated in RMC tumor cells of patients treated with ICT, suggesting that p300 is specifically engaged during RMC hyperprogression." (PMID 41290625, 2025). "The exact cause of this predisposition remains unknown, but it is hypothesized that the lack of tumor suppressor activity of CREBBP may contribute to the development of malignancies." (PMID 40507954, 2025). "Thus, CREBBP and EP300 may have distinct functions in prostate carcinogenesis, depending on tumor stage and cell model used." (PMID 33705753, 2021). "Additionally, some of the other mutations that we identified in our screen of the 105C cell line (e.g., CREBBP) appear in other OCCC cell lines and tumour samples, suggesting that these genes may play a yet unidentified role in a subset of these cancers." (PMID 33153119, 2020). "In addition, CREB-binding protein (CBP; also known as KAT3A), the paralog of p300 encoded by the CREBBP gene, was not significantly upregulated in RMC tumor cells following ICT (log2FoldChange 0.13, P-value > 0.5), suggesting that p300 is specifically engaged during RMC hyperprogression." (PMID 41290625, 2025).